IFNG (interferon gamma)
Diseases named in the same sentence as IFNG in open-access papers (continued):
Sharing a sentence is not in itself a finding about the gene and the disease.
co-infection (continued). "Moreover, Ad5/3-DMFE was significantly superior to all other viruses regarding IFNγ secretion and to the co-infection strategy regarding CD69 expression on CD8+ T cells." (PMID 41552759, 2026). "For example, co-infection of Map with M. bovis has been shown to have an effect on the immunological response to tuberculins leading to false negative results and affecting the sensitivity of the M. bovis skin test and interferon gamma assay." (PMID 33789575, 2021). "Co-infection of E. maxima with C. perfringens suppressed the expression of IFNα, IFNγ, IL-1β, IL-2, IL-12, IL-13, IL-17, NO, and transforming growth factor-β4 genes, but increased the expression of IL-8, IL-10, IL-15, and lipopolysaccharide-induced TNFα factor." (PMID 33193291, 2020). "In co-infection with B. malayi and M. tuberculosis, the decreased function of DCs and macrophages to migrate and present antigens to T cells results in decreased expression of cytokines such as IL-10, IFNα, and IFNγ." (PMID 33193291, 2020). "Interestingly, only CD4+ T cells showed the most prominent induction of IFNγ expression and increase in IFNγ+ numbers upon co‐infection." (PMID 29113976, 2018). "Taken together, CD4+ T cells are the major contributors of higher splenic IFNγ during co‐infection." (PMID 29113976, 2018). "Co‐infection induces higher IFNγ levels in the spleen compared to single PbA infection." (PMID 29113976, 2018). "The IFNγ‐dependent mechanism described here induced by co‐infection with CHIKV could possibility alter or delay CD8+ T‐cell migration to the brain, leading to disease aggravation." (PMID 29113976, 2018). "The source for IFNγ were most likely T cells, since NK cells, which contribute to early IFNγ production during M. tuberculosis infection, were significantly decreased in numbers during co-infection." (PMID 26913029, 2016). "We hypothesized that helminth-elicited Th2 cells were being converted into IFNγ-secreting Th1 cells during Plasmodium co-infection, as pressure to control both pathogens was placed on the Th cell population." (PMID 26147567, 2015). "Finally, we found that blockade of IL-12 and IFNγ during Plasmodium and helminth co-infection preserved Th2 responses and IgE production, but was insufficient to fully restore anti-helminth immunity." (PMID 26147567, 2015). "Finally, blockade of IL-12 and IFNγ during co-infection partially preserved anti-helminth Th2 responses." (PMID 26147567, 2015). "Overall, this study provides fresh insight into the functional relationship between IFNγ- and IL-4-producing Th cells during co-infection and indicates that limiting acute Th1 responses may preserve Th2-mediated anti-helminth immunity." (PMID 26147567, 2015). "Because BV and T. vaginalis co-infections are so prevalent in C. trachomatis infected women, the role they play in supplementing local tryptophan, compromising IFNγ-mediated immunity and aiding establishment of chronic infections is also critical." (PMID 24959423, 2014). "The reduced cytokine responses to TB antigens in HIV co-infection, and in particular IFNγ responses, concurs with previous studies, and might be expected to result in increased susceptibility to TB infection and disease as has been reported before." (PMID 25372043, 2014). "In this study, a co-infection of FV together with the lactate dehydrogenase-elevating virus (LDV) resulted in a reduced FV-specific CD8 T cell response mediated by the strong LDV-dependent IFNγ production." (PMID 23738889, 2013). "Though there is evidence that co-infection with MAP can reduce the sensitivity of the IFNγ test for bovine tuberculosis there is no strong evidence that natural infection with MAP affects the specificity of the IFNγ test." (PMID 24308747, 2013). "Similarly, PLV co-infection appears to focus the innate immune response to FIV infection by limiting variability in IFNγ expression across tissues." (PMID 22069521, 2011).
co-infection (continued). "Furthermore, it has been observed that the chemokines MIG and IP-10 are present at elevated levels in asymptomatic co-infection, in response to the increased expression of interferon-gamma (IFN-γ), which has been shown to be negatively regulated by HIV in vitro." (PMID 37999614, 2023). "Comparable severity of cecal pathology between Hh+Hp and mono-Hh mice was in agreement with the finding that co-infection with Hp did not significantly enhance cecal transcription of key ILCs 1/3-associated genes including Ifnγ, Tnfα, Il-1β, and Il-17A at 21 WPI." (PMID 33255175, 2020). "However, as helminth infections can modulate host IFNγ responses, co-infections with these parasites could have serious consequences for the reliable detection of other important pathogens (see section Mycobacterium tuberculosis)." (PMID 30467504, 2018). "The slower impact of the DNac mutant on Brucella could be due to the fact that it induces IFNγ less rapidly in spleen as demonstrated by the reduced frequency of IFNγ-producing cells in the spleen of DNac T. brucei-infected mice early in co-infection compared to wild-type T. brucei-infected mice." (PMID 28824630, 2017). "Thus, IL-12 and IFNγ play a major role compromising Th2 responses during helminth/ Plasmodium co-infection, but additional factors also contribute to compromised anti-helminth immunity during co-infection." (PMID 26147567, 2015). "We therefore hypothesized that the loss of Il4gfp+ Th2 cells in the mesenteric lymph nodes and the increase in Ifngyfp+ cells in the spleen during H. polygyrus and P. chabaudi co-infection was due to conversion of Th2 cells to an IFNγ-producing Th1-like phenotype." (PMID 26147567, 2015). "In contrast, this co-infection in RAG2 females downregulated expression of several cytokines such as Il-1β, Il-17A, Ifnγ, Tnfα, and Il-13 only at 10 WPI, but increased transcription of colonic Il-22 at 21 WPI." (PMID 33255175, 2020). "Flow cytometric profiling and ELISPOT assays of isolated CD4+ T cells also showed that Plasmodium co-infection abrogates infiltration of activated (LFA-1+) and IFNγ-secreting CHIKV-specific CD4+ T cells into the joints." (PMID 30254309, 2018). "This difference was comparable to those observed using ELISPOT and flow cytometry, and collectively suggest that in the setting of HIV/CMV co-infection, HIV MDSC restrict CMV-specific CD4+ T cell IFNγ production." (PMID 28338007, 2017). "GLM analyses were performed to further investigate the differences in IFNγ mRNA expression between FIV single and PLV/FIV co-infection at an individual tissue level." (PMID 22069521, 2011). "Previous studies have demonstrated lower eosinophil counts, decreased production of IL-5, and increased production of interferon gamma in patients with S. stercoralis and HTLV-1 co-infection." (PMID 19513105, 2009). "Upon re-stimulation of lymph node cells with H1 in vitro, the antigen-specific production of IFNγ, IL-17, or IL-10 was not affected by N. brasiliensis co-infection." (PMID 36753434, 2023). "In both WT and IFNγ-/- mice, concurrent co-infection presented similar pathologies with reduced joint swelling, suggesting that IFNγ is not a mediator of pathological changes to CHIKV disease during concurrent PbA and CHIKV co-infection." (PMID 30254309, 2018). "Co-infection did not alter parasitaemia when compared to single Py17x-infected mice in WT or IFNγ-/- background." (PMID 30254309, 2018). "For neutrophils, while IFNγ expression is high in all four groups, the difference between single PbA infection and co‐infection was a result of neutrophils reduction in single PbA infection and not an increase in IFNγ expression level in the co‐infected mice." (PMID 29113976, 2018). "Therefore, the effects of concurrent CHIKV + PbA co-infection and pre-Py17x (−4 dpi) + CHIKV infection were investigated in IFNγ-/- mice." (PMID 30254309, 2018).
co-infection (continued). "Importantly, in this study, we provide the first evidence of IL-27 mediated regulation of IFNγ and IL-10 during human CMV infection in the setting of HIV co-infection." (PMID 28338007, 2017). "Because IFNγ levels were increased and T cell responses not impaired during P. yoelii co-infection, we reasoned that the reduction in NK cell numbers had no consequences on disease outcome." (PMID 26913029, 2016). "Defects in the interleukin-12 (IL12) and interferon γ (IFNγ) pathway have been recognized as factors in co-infection with non-tuberculous mycobacteria and non-typhoidal salmonella." (PMID 24209898, 2013). "Independent of HIV co-infection, IFNγ+ CMVpp65-specific CD4+ T cell frequencies increased with age." (PMID 25974183, 2015). "However, IFNγ was elevated in the lung tissue of all Pcc infected mice, regardless of Nb co-infection, at day 7 pi." (PMID 19951425, 2009). "Importantly, although blocking IL-12 and IFNγ during co-infection did not retain fulminant anti-helminth immunity, it did preserve Th2 cell numbers and serum IgE, highlighting a novel mechanistic pathway of how Plasmodium infection negatively impacts anti-helminth Th2 responses." (PMID 26147567, 2015). "Ad5 viral load from LV-CMV-IFNγ co-infected cells was significantly lower than that from LV-CMV-GFP co-infection (P = 0.032), which suggested that IFNγ rather than GFP could further enhance the inhibition of Ad5 replication in the recombinant lentivirus co-infected cells." (PMID 22916129, 2012). "IFNγ release to QFT-IT was not significantly different between the four matched groups, confirming that QFT-IT cannot distinguish LTBI from active TB in patients with or without HIV-co-infection." (PMID 28837654, 2017). "In addition, we show that IL-27 controls IFNγ and mediates IL-10 producing Tr1 cells during CMV infection, with or without co-infection with HIV." (PMID 28338007, 2017).
hepatocellular carcinoma (194 papers, 2007 to 2026). A malignant tumor that arises from hepatocytes. "In the context of mouse tumor models, NR4A1 (Nuclear Receptor 4A1) has emerged as a significant player, mediating NK-cell dysfunction in hepatocellular carcinoma through the IFNγ/p-STAT1/IRF1 pathway." (PMID 39920136, 2025). "Stimulation of hepatocellular carcinoma cells with IFNγ led to an increase in the amount of IRF1 and, subsequently, the amount of PD-L1 in the cells." (PMID 38396830, 2024). "The results suggested that the targeted delivery of IFNG by the PEI-Fe3O4/pYr-ads-8-5HRE-cfosp-IFNG albumin nanospheres was effective in inhibiting the proliferation of hepatoma cells." (PMID 37091158, 2023). "Our experiments demonstrated that the PEI-Fe3O4/pYr-ads-8-5HRE-cfosp-IFNG albumin nanospheres system is a comprehensive treatment method for hepatoma, which can effectively combine immune genre therapy with hyperthermia." (PMID 37091158, 2023). "The results presented in this study demonstrate the successful synthesis and preparation of PEI-Fe3O4/pYr-ads-8-5HRE-cfosp-IFNG albumin nanospheres for targeted delivery of IFNG to hepatoma cells." (PMID 37091158, 2023). "The therapeutic effect of PEI-Fe3O4/pYr-ads-8-5HRE-cfosp-IFNG albumin nanospheres on hepatocellular carcinoma was investigated by cell and animal experiments." (PMID 37091158, 2023). "For instance, in hepatocellular carcinoma, treatment of MSCs with IFNγ and TNFα leads to a high expression level of TGFβ which in turn induces EMT-related properties in tumor cells." (PMID 35251985, 2022). "A study investigated the effect of IFNγ on hepatocellular carcinoma (HCC) found that IFNγ enhanced the consumption of GSH, increased lipid peroxidation, and increased the sensitivity of HCC to ferroptosis." (PMID 35619718, 2022). "This study aimed to investigate the effects of tumor-related cytokines, interferon gamma (IFNγ), and tumor necrosis factor alpha (TNFα) on PD-L1 expression in human hepatocellular carcinoma cells, HepG2." (PMID 34445462, 2021). "In this study, we confirmed that TNFα significantly augments the PD-L1-inductive effect of IFNγ in HepG2 cells, a human hepatocellular carcinoma cell line, and this effect was through activation of STAT1, JNK, and NFкB pathways." (PMID 34445462, 2021). "Very recent work demonstrates an important role for NAD+ in STAT1 activation and PD-L1 induction by IFNγ in hepatocellular carcinoma cells." (PMID 34726598, 2021). "To evaluate the effect of EZH2 on PD-L1 expression, we used different hepatoma cell lines treated with IFNγ, which is a potent PD-L1 induction factor in multiple tumors." (PMID 31727135, 2019). "In vitro cell experiments revealed that EZH2 negatively regulated the PD-L1 expression of hepatoma cell lines in IFNγ-dependent manner." (PMID 31727135, 2019). "Immunoblotting assays showed that the effective EZH2-targeted siRNAs enhanced IFNγ-induced PD-L1 expression in hepatoma cell." (PMID 31727135, 2019). "In the present study, we reported that the epigenetic modifier EZH2 negatively regulated IFNγ-induced PD-L1 expression in hepatoma cells." (PMID 31727135, 2019). "Inhibiting EZH2 by GSK126 or DZNep treatment effectively increased IFNγ-induced PD-L1 expression in hepatoma cells." (PMID 31727135, 2019). "For example, SelP expression is downregulated by TNFα stimulation of 3T3-L1 cells, by IL-6 in human hepatoma cells, and studies of the human SelP promoter have shown it is responsive to IL-1β, IFNγ and TNFα in HepG2 cells." (PMID 30571741, 2018). "In a recent study,DDX60L was newly identified as a gene differentially expressed in response to IFNγ in Huh7 as compared with Huh6 hepatoma cells, the latter of which are refractory to IFNγ-mediated inhibition of HCV31." (PMID 29568506, 2018). "Promising results were obtained with combination of low-dose 5-fluorouracil with recombinant interferon-gamma (IFN-γ) in patients with advanced hepatocellular carcinoma." (PMID 29780381, 2018).
hepatocellular carcinoma (continued). "For instance, DCs pulsed with hepatocellular carcinoma cell (HCC)-derived exosomes led to an increase in IFNγ levels and CD8+ T cells, and in the reduction of IL10 and TGF-β levels in HCC-bearing mice." (PMID 29515996, 2018). "TCR-transduced T cells were polyfunctional, secreting the cytokines interferon gamma, tumor necrosis factor alpha and interleukin-2, and effectively killed hepatoma cells replicating HBV." (PMID 28792537, 2017). "In fact, induction of IL-36γ was detected in cultured murine primary hepatocytes or human Huh7 hepatocellular carcinoma cells exposed to inflammatory IL-1/TNFα/IFNγ." (PMID 25687687, 2015). "Interestingly, KPA-treated livers displayed an upregulation of interferon gamma-related pathways, that has well-established antifibrogenic effects and anti-tumor effects in hepatocellular carcinoma (HCC)." (PMID 40862768, 2025). "Moreover, recent reports demonstrated that IL-1β can activate the STAT1 pathway by negatively modulating ERK2 activation in the target cells and synergistically elevates PD-L1 expression through the coordination with IFNγ in hepatocellular carcinoma." (PMID 38166970, 2024). "Furthermore, IFNγ enhanced the JAK-STAT signal pathway to activate ferroptosis in hepatocellular carcinoma cells." (PMID 38575966, 2024). "In another study, in hepatocellular carcinoma, treating MSCs with tumor necrosis factor-α (TNF-α) and interferon γ (IFNγ) causes an increase in production of TGFβ by MSCs which in turn could promote tumor metastasis by inducing EMT in cancer cells." (PMID 35251985, 2022). "In this study, we observed that downregulating the EZH2 could enhance IFNγ-induced PD-L1 expression in hepatoma cells." (PMID 31727135, 2019). "Furthermore, qPCR, immunoblotting, and flow cytometry analyses confirmed that IFNγ-induced PD-L1 expression was upregulated in a variety EZH2-silenced hepatoma cells." (PMID 31727135, 2019). "Moreover, apigenin is shown to induce apoptosis of human hepatocellular carcinoma HepG2 cells through the releases of IFNγ." (PMID 28526810, 2017). "We evaluated whether IFNα, IFNγ and IFNλ down-regulate β-catenin in hepatocellular carcinoma (HCC) cell lines, HepG2 and Huh7." (PMID 23056571, 2012). "A low level of IRF8 expression in tumors is associated with poor prognosis in human hepatocellular carcinoma (HCC), and gene set enrichment analysis identified the IFNγ and PD-1 signaling signatures as the top suppressed pathways in patients with IRF8-low HCC." (PMID 36672246, 2023). "In patients with hepatocellular carcinoma (HCC), compromised anti-tumor potency of γδ T cells was observed and Treg isolated from HCC tissue were suppressive of IFNγ production and tumor cell cytotoxicity by γδ T cells." (PMID 37928540, 2023). "Also in hepatocellular carcinoma (HCC) cells an IFNγ induced PD-L1 expression was observed." (PMID 32486375, 2020). "The percentage of IFNγ+ T cells in peripheral blood is downregulated persistently during the tumor growth progressively among the B16-F10 pulmonary metastatic and H22 intraperitoneal hepatoma models, while in the BMSC-treated mice groups the percentages of IFNγ+ T cells were elevated about 15%." (PMID 25889932, 2015). "Accumulating evidence demonstrates that DC-based vaccines significantly enhance the proliferation and activation of CD8+ T lymphocytes while elevating serum interferon-gamma (IFN-γ) levels in patients with hepatocellular carcinoma (HCC), thereby contributing to improved overall survival (OS)." (PMID 40242773, 2025). "In fact, the functional analysis of CD8+ T cells in hepatocellular carcinoma showed that the PD-1-high sub-population produced the lowest amounts of tumour necrosis factor (TNF) and/or interferon-gamma (IFN-γ) upon T cell receptor stimulation." (PMID 35982052, 2022).
hepatocellular carcinoma (continued). "TNFα and IFNγ upregulate FAT10, which increases susceptibility to inflammation-driven diseases like nonalcoholic fatty liver disease (NAFLD), non-alcoholic steatohepatitis (NASH), and hepatocellular carcinoma (HCC)." (PMID 36386217, 2022). "In hepatocellular carcinoma (HCC), tumour-derived monocytes have been found to induce dysfunctions in NK cells that were impaired in their ability to produce TNFα and IFNγ." (PMID 33569050, 2020). "In the present study, we found that hepatoma cells expressed high levels of EZH2, which abrogated PD-L1 upregulation by IFNγ." (PMID 31727135, 2019). "Hepatoma cells expressed high level of EZH2, and had only marginally increased PD-L1 expression upon IFNγ stimulation." (PMID 31727135, 2019). "The use of IL‐21 in solution in the priming of NK cell culture resulted in an improved NK cell proliferation, without compromising cytotoxicity potential or interferon gamma secretion against hepatocellular carcinoma cell lines." (PMID 39865344, 2025). "For example, EZH2 methyltransferase activity in hepatocellular carcinoma cells caused H3K27me3 histone modification near IRF1 and CD274 promoter regions, which suppressed their expression without affecting the IFNγ/STAT1 signaling pathway." (PMID 38396830, 2024). "To investigate the effect of HLF hepatocellular carcinoma cells on the M1 polarization of THP-1-derived macrophages, we treated homospheroids (containing only macrophages) and heterospheroids (containing both macrophages and HLF cells) with M1 inducers (IFNγ and LPS)." (PMID 41440012, 2025). "For instance, in hepatocellular carcinoma (HCC), tumor-educated MAIT cells upregulate inhibitory molecules like PD-1, CTLA-4, and TIM-3, strongly decreasing IFNγ, IL17, GZM B, and perforin production." (PMID 40422223, 2025). "Also, CD28−Tim-3+CD4+ T cells from patients with hepatocellular carcinoma were reported to exhibit impaired ability to produce of IL-2 and IFNγ but their possible exhausted status was not ruled out." (PMID 34386013, 2021).